MAP2 (microtubule associated protein 2)
Diseases named in the same sentence as MAP2 in open-access papers (continued):
Sharing a sentence is not in itself a finding about the gene and the disease.
infection (continued). "MAP2 immunoreactivity of many neurons was also increased at 48 h post-infection compared to control cells." (PMID 26834627, 2015). "We found a significant reduction in both MEF2C and MAP2 mRNA expression and protein levels after infection with lenti-shMEF2Cs." (PMID 21901155, 2011). "A co-staining of viral protein ICP0, glycoprotein C (gCp), and HSV-1 GFP with neuronal markers MAP2/TUJ-1 suggested the localization of these proteins on the edges of the organoids at 48 h acute infections, whereas the neuronal markers localized mostly in the cores of COs." (PMID 39176174, 2024). "Additionally, dsRNA was detected in both the neuronal bodies and axons of the MAP2-positive cells at 48 h after infection." (PMID 35215199, 2022). "A total of 14 days after the infection, triple staining against EGFP, TH, and MAP2 (microtubule associated protein 2) showed that many of the MLN-EGFP-infected AS expressed both TH, the specific marker of DA neurons, and MAP2, the marker of mature neurons." (PMID 34830023, 2021). "Consequently, the purpose of this study was to investigate the effect of infection with rabies virus on the expression of two cytoskeletal proteins (MAP2 and NF-H) and its link to dendritic pathology in neurons of the ventral horn of the mouse spinal cord." (PMID 29509660, 2018). "However, by 3 weeks post-infection, beclin 1 knockdown resulted in a significant decrease in the number of surviving MAP2+ neurons, supporting previous findings that neurons with decreased levels of beclin 1 degenerate in vivo." (PMID 26692002, 2015). "In addition, Lenti-shSOCS3 infection results in more and longer MAP-2+ dendrites after complete SCI." (PMID 26384335, 2015). "Therefore, higher MeP-MECP2e2 multiplicity of infection (MOI) was used to obtain MAP2 positive neurons with detectable MYC signals." (PMID 25644311, 2015). "However, significantly more MAP-2+ dendrites were seen in spinal cords of Lenti-shSOCS3-infected animals as compared to those with Lenti-pGipz infection." (PMID 26384335, 2015). "Furthermore, extensive microtubule-associated protein 2 (MAP2) reactivity also was seen at 24 and 48 h post-infection." (PMID 26834627, 2015). "Similarly, fluorescence staining for MAP2 suggested that both the cell bodies and the dendrites remained intact in the infected area, even at the late infection stage." (PMID 23114630, 2013). "Given that SARS-CoV-2 could infect MAP2+ post-mitotic neurons, we next analyzed the composition of excitatory neurons to validate their cortical identity and to investigate their susceptibility to SARS-CoV-2 infections." (PMID 36327326, 2022). "After 24 h of infection, the cells were fixed and analyzed by confocal laser scanning microscopy using indirect immunofluorescence stainings against RABV nucleoprotein N, neuron marker MAP2 (microtubule-associated protein 2) and astrocyte marker GFAP (glial fibrillary acidic protein)." (PMID 32053954, 2020). "On day14 post-infection, immunostaining with astrocytic (GFAP) or neuronal (MAP2 and TUJ1) markers showed that NeuroD1-infected cells displayed decreased GFAP signal (91.6 ± 2.5% → 48.3 ± 1.4%) and exhibited neuronal morphology in both GFAP + and GFAP − cells." (PMID 39014391, 2024). "Before the infection with HSV-1, COs were characterized by IHC for brain cell types including neurons, microglia, astrocytes, and oligodendrocytes using MAP2/TUJ-1-, IBA1-, GFAP-, and Olig2-specific antibodies, respectively." (PMID 39176174, 2024). "Although subject to further investigation, additional stainings for the neuronal marker MAP2 and the astrocyte marker GFAP indicate that the morphology and/or integrity of both NSPH cell types is severely affected following infection with VZVORF65-tdT-66." (PMID 39351233, 2024). "After 24 h of infection at a MOI of 2, cultured cells were immunostained with anti-MAP2 antibody and counter-stained with DAPI." (PMID 36680255, 2023).
infection (continued). "The number of astrocytes (by expression of GFAP), microglial (by Iba1), and neuronal cells (by MAP-2) in the brain following IM and IC inoculations of SRV were evaluated by immunohistochemistry and H & E staining 7 to 30 days post-infection." (PMID 34712425, 2021). "At 10 days post-infection CHNs were subjected to IF-ICC with an anti-Homer1 mAb and an antibody against the dendritic marker MAP2." (PMID 31566565, 2019). "Our results indicate that SeVdp(ABMN) infection reprogrammed MEFs into morphologically neuron-like cells, and that these cells expressed typical neuronal markers, including β-III Tubulin, MAP2, and Synapsin I." (PMID 28978921, 2017). "Such increases/protection effects on MAP-2+ dendrites were still observed in both the ventral and dorsal horns of spinal cord 4 weeks after complete SCI as compared to Lenti-pGipz infection." (PMID 26384335, 2015). "Quantitative analyses demonstrated that both Lenti-shSOCS3 and Lenti-shSOCS3 #2 infection increased the number of long MAP-2+ dendrites in both ventral and dorsal horn of spinal cord 1 week after complete SCI as compared to Lenti-pGipz infection." (PMID 26384335, 2015). "The spinal cord was completely transected 2 weeks after Lenti-shSOCS3 or Lenti-pGipz infection, and then 1 or 4 weeks after SCI the animal was sacrificed and immunostained with MAP-2 antibody." (PMID 26384335, 2015). "In contrast, when compared to Lenti-pGipz infection, reduction of SOCS3 expression by Lenti-shSOCS3 resulted in longer MAP-2+ dendrites at both 1 and 4 weeks after SCI." (PMID 26384335, 2015). "Infection of GFAP and MAP2-positive cells was confirmed by the use of orthogonal sections." (PMID 38514653, 2024). "Immunofluorescent staining with MAP2 revealed that LGK974 significantly shortened the neurites length of Tfg‐knockdown neurons on day 8 after infection, while LGK974 itself did not affect the neurite outgrowth in control neurons." (PMID 35986567, 2022). "In line with previous observations, this neural culture displayed higher levels of neuronal marker MAP2, compared with glial marker GFAP, and can be infected all lyssavirus strains, with high levels of viral RNA and protein detectable 72 hours post-infection (h.p.i)." (PMID 35004351, 2021). "Whilst the Z.Dog strain was able to infect the MAP2-positive neurons in the inoculated panel, the spread of infection to neurons in the non-inoculated panel was significantly reduced compared to CVS-11." (PMID 32218146, 2020). "This was normalized to the MAP2 positive area or total protein and therefore is independent of neurotoxicity induced by infection." (PMID 32390638, 2020). "We showed that infection of CGNs with 22L strain triggered neuronal dysfunction as inferred by the fragmentation of axon and dendrites by 11 days post-infection (dpi), using SMI31 and MAP2 as markers of the axon and dendrites, respectively." (PMID 26241960, 2015). "Quantitative assessment of these results showed that MAP2+ neurons, co-stained with GFP to indicate lenti-infection, underwent far less neuronal differentiation if the cells were infected with lenti-shMEF2C-1- or -2 compared to control infection." (PMID 21901155, 2011). "Furthermore, we found that TIGR4 co-localized with β-actin of neuronal cells, stained using the specific marker MAP2, while infection with the mutant TIGR4ΔrrgA showed no co-localization between the bacteria and neuronal β-actin." (PMID 33760879, 2021). "Increases in MAP2 staining post-infection were not expected, but are not unreasonable." (PMID 26834627, 2015). "Interestingly, MAP2 levels did not change significantly across groups, which may be because of the relatively short duration of infection in this retrospective study cohort." (PMID 24420448, 2014). "RSMHV2(P) showed the single-cell infection of majorly non-neuronal cells in the culture, as shown by a large number of EGFP-positive cells, but reduced the colocalization with MAP2-positive cells." (PMID 36680255, 2023).
infection (continued). "However, general infection-induced denervation does not appear to be a cause of cardiac disfunction during this stage of the infection, at least based on the expression of transcripts encoding the pan-neuronal marker protein PGP9.5 or MAP2, a structural marker associated with dendritic growth." (PMID 38003828, 2023). "Despite robust infection in these macrophages, supplementation of i3 neurons with HIV-MDM supernatants did not reduce the number of MAP2+ cells relative to mock supernatants, even at a supplementation ratio of 1:4." (PMID 38348237, 2023).
cancer (19 papers, 2016 to 2025). A tumor composed of atypical neoplastic, often pleomorphic cells that invade other tissues. "We also found heterogeneous MAP2 expression in the majority of cases and many MAP2-positive TMA spots revealed both MAP2-positive and MAP2-negative cancer areas." (PMID 38310601, 2024). "When upregulated, MAP2 stimulates cancer cell proliferation and seems to play an important role in tumor progression." (PMID 38267453, 2024). "Kaplan Meier analysis showed a significant correlation between strong MAP2 staining in carcinoma and shortened BCR-free survival after prostatectomy (p < 0.001)." (PMID 38310601, 2024). "Survival analysis showed a significant correlation between strong MAP2 staining in carcinoma and shortened biochemical recurrence-free survival after prostatectomy (p < 0.001)." (PMID 38310601, 2024). "The introduction of MAP2 into metastatic cancer cells interfered with microtubule assembly, leading to the in vitro suppression of cell migration and invasion." (PMID 36188577, 2022). "IQGAP1+ staining was observed in neurons (Map2+ cells), in cancer stem cells (CSC; nestin+) and in several macrophages (CD31+ or Iba1+)." (PMID 28098764, 2017). "Interestingly, high MAP2 expression in PIN lesions correlated with the presence of simultaneous high-grade carcinoma (ISUP 4–5) (p = 0.019)." (PMID 38310601, 2024). "MAP2, a crucial regulator of microtubule dynamics, exerts dual effects on cancer progression." (PMID 36765702, 2023). "This suggests that MAP2 expression shows cancer-type specificity." (PMID 36188577, 2022). "Consistently, MAP2 knockdown was shown to impair cancer cell migration." (PMID 36188577, 2022). "Finally, A-site binding to 80S ribosomes might occur only under specific conditions, such as physiological stress or upregulation of MAP2 levels, as reported in different cancer cells." (PMID 38267453, 2024). "However, the molecular mechanism behind the regulation of cancer metastasis by MAP2 is largely unknown." (PMID 36188577, 2022). "Several cancer and developmental studies have suggested a role for Akt3 in cellular migration, and demonstrated that the downregulation of Akt3 increases migration and metastasis, and MAP-2+ neurons in neurospheres expressing Akt3 with a specific mutation at E17K, have a defect in migration." (PMID 31404142, 2019). "In our eight signature genes (ARL6IP4, ATP2A1, CRYAB, ELFN2, MAP2, MAT1A, ORC1, and POU4F1), prior research has elucidated the expression and function of several genes involved in the initiation and progression of cancer." (PMID 41567198, 2025). "Poorly differentiated carcinomas (ISUP 4–5, n = 58) were strongly stained in 63.8%, whereas MAP2 was significantly less expressed in carcinomas with ISUP Grade Group 1–3." (PMID 38310601, 2024). "GSCs showed characteristics consistent with cancer stem cells: namely, neurosphere formation; expression of stem cell markers Sox2 and OLIG2 and multilineage differentiation with markers for astrocytes (GFAP), neurons (MAP2) or oligodendrocytes (O4)." (PMID 37997289, 2024). "In both carcinoma and PIN lesions, MAP2 staining correlated with the preoperative PSA value." (PMID 38310601, 2024). "For cancer, identified targets include VEGFB, VEGFR2, MAP2, MMP14, HNF1A, TUSC5 and KLF12." (PMID 35356223, 2022). "Four CRs (TRRAP, EP300, NSD2 and MSH6) having synthetic lethal interactions with MAP2 were integrated as a MAP2 CSL module in COAD, where MAP2 was affected by two taxnes (Paclitaxel and Docetaxel).These four CRs play roles in cell cycle, notch signaling pathway and mismatch repair in human cancers." (PMID 36180906, 2022). "In addition, E2F1 and MAP2 are suggested as molecular targets for UVB first line of response that could be used to monitor proteins altered in genotoxic stress and/or molecular targets in cancer." (PMID 34068980, 2021). "miR-484 is a key factor in cancer and non-cancerous diseases, and its targets in cancer include VEGFB, VEGFR2, MAP2, MMP14, HNF1A, TUSC5, and KLF12." (PMID 36572856, 2022).
neurodegenerative disease (8 papers, 2012 to 2024). A disorder of the central nervous system characterized by gradual and progressive loss of neural tissue and neurologic function. "The present study demonstrates a strong relation between IRAP and the microtubule variant MAP2, and furthermore, the neurodegenerative disease marker GFAP is also altered by IRAP inhibition." (PMID 39596085, 2024). "Disorganization between the MTs and MAP-2 is linked to many neurodegenerative diseases." (PMID 38139072, 2023). "Notably, some of the BA genes we identified, such as MAP2 and MAPT known for their involvement in brain asymmetry and neurodegenerative diseases, have also been implicated in previous studies." (PMID 37561991, 2023). "The proteins encoded by these genes may play a coordinated role in the brain with the proteins tau, MAP-2, SYN, and CALM family in neurodegenerative diseases, which may be novel biomarkers of neurodegenerative diseases caused by aging." (PMID 34733151, 2021).
neurological diseases (8 papers, 2012 to 2025). "MAP2, encoding microtubule-associated protein 2, serves as a crucial regulator of the neuronal dendritic cytoskeleton and is implicated in various neurological disorders." (PMID 40446031, 2025). "Alterations in MAP-2 expression have been documented in rabies and many neurological diseases, although there is still little known about changes in this protein due to rabies." (PMID 34712425, 2021). "Springer and his co-workers have proposed that MAP2 decreased dramatically within 1 hour after traumatic spinal cord injury, which is believed that as somatodendritic compartments of neurons, MAP2 may be especially vulnerable during diseases of nervous system." (PMID 22272295, 2012).
neurodevelopmental disorder (2 papers, 2023 to 2026). A behavioral and cognitive disorder with onset during the developmental period that involves impaired or aberrant development of intellectual, motor, or social functions. "One particular sub-neurotoxic phenotype that is relevant in neurodevelopmental disorders is alterations in spine density and morphology, which would not have been captured via our studies of MAP2 morphology and may underlie some the observed changes in neuronal activity." (PMID 38348237, 2023).
bacterial infection (1 paper, 2015). "This study demonstrates that E. faecalis increases both Alz-50 and CP13 reactivity, as well as that of microtubule-associated protein 2 (MAP2), in cortical cultured neurons; and provides support for the hypothesis that bacterial infection may play a potential role in Alzheimer pathology." (PMID 26834627, 2015).
peripheral neuropathy (1 paper, 2016). A disorder affecting the peripheral nervous system. "The failure to detect changes in chemotherapy-induced peripheral neuropathy in adult NMNAT2+/- mice cannot be attributed to compensatory changes in other NMNAT isoforms, NMNAT enzyme activity or changes in MAP2 or neurofilament levels in adult DRG." (PMID 26808812, 2016).
MAP2 also shares sentences with these, for which no sentence is quoted: psychiatric disorder (3 papers); bipolar depression (2); delirium (2); developmental delay (2); ependymoma (2); microcephaly (2); Parkinson (2); Rett syndrome (2); adenocarcinoma (1); amyotrophic lateral sclerosis (1); Arthritis (1); Behavioral Abnormalities (1); Brain atrophy (1); central neurocytoma (1); cerebral infarction (1); Chagas disease (1); Chorea (1); colon carcinoma (1); cutaneous melanoma (1); dysplastic nevi (1); Dystonia (1); embryonal tumors (1); endometrial adenocarcinomas (1); endometrial cancer (1); fatal familial insomnia (1); Flavivirus Infections (1); HCMV infection (1); heart failure (1); HIV encephalitis (1); Hyperglycemia (1).
A further 31 diseases each share a sentence with MAP2 in 1 paper.